CDCA2 (cell division cycle associated 2)
Diseases named in the same sentence as CDCA2 in open-access papers (continued):
Sharing a sentence is not in itself a finding about the gene and the disease.
cancer (32 papers, 2013 to 2025). A tumor composed of atypical neoplastic, often pleomorphic cells that invade other tissues. "Cell Division Cycle Associated 2 (CDCA2) is a cell cycle related protein, which has been documented to be upregulated in other types of cancer." (PMID 40565058, 2025). "Aberrant expression of the Mklp2-encoding KIF20A gene and the RepoMan-encoding CDCA2 gene have been observed in a variety of cancers and significantly correlates with survival outcomes." (PMID 38806145, 2024). "Tumors are diagnosed and forecasted with a high degree of accuracy by CDCA2, and the quantity of expression CDCA2 is linked to the prognosis of many cancers." (PMID 37733705, 2023). "The CDCA2 gene encodes a subunit of protein phosphatase 1, which is associated with cell cycle and has relatively higher expression in cancer conditions." (PMID 32193399, 2020). "CDCA2 (cell division cycle associated 2), a member of cell cycle-related proteins, regulates cell proliferation and is involved in the development of various cancers." (PMID 39273692, 2024). "Additionally, the diagnostic and prognostic significance of CDCA2 in pan-cancer was also evaluated using receiver operating characteristic (ROC) and Kaplan–Meier (KM) curves." (PMID 37733705, 2023). "All these results suggest that CDCA2 had an extensive diagnostic and prognostic value in cancers." (PMID 37733705, 2023). "Our findings show that CDCA2 might be a diagnostic and prognostic biomarker and therapeutic target in pan-cancer, particularly in LGG." (PMID 37733705, 2023). "The ROC curve was utilized to assess CDCA2 diagnostic values in pan-cancer." (PMID 37733705, 2023). "Correlation between CDCA2 and Ki-67 expression have been examined in various cancer types, yet reporting contradictory findings." (PMID 40565058, 2025). "CDCA2 differential expression was studied in pan-cancer and in diverse molecular and immunological subgroups in this research." (PMID 37733705, 2023). "The TISIDB website was used to investigate the differential expression of CDCA2 in distinct molecular and immunological subtypes of pan-cancer." (PMID 37733705, 2023). "CDCA2 demonstrated excellent predictive performance (AUC > 0.9) in 20 distinct types of cancer, according to the findings of the ROC curve." (PMID 37733705, 2023). "CDCA2 can serve as a novel biomarker for the diagnosis and prognosis in pan-cancer, especially in LGG." (PMID 37733705, 2023). "In 11 different kinds of cancer, survival study revealed that the amount of CDCA2 expression was shown to be connected with OS, DSS, and PFI." (PMID 37733705, 2023). "The cellular function of CDCA2 in cancerous cells has also been investigated in several cancer types, and CDCA2 is mainly involved in promoting tumor cell proliferation by preventing G1 phase arrest and inhibiting apoptosis." (PMID 35694386, 2022). "Later, it was found that CDCA2 was closely related to DNA damage and cell cycle, and the role of CDCA2 in cancers has also received more and more attention." (PMID 36588796, 2022). "CDCA2 regulates cell cycle progression in different cancers in part by affecting the expression of cell cycle regulatory molecules." (PMID 35694386, 2022). "As not all cell cycle regulatory proteins have been examined in previous studies, we believe that the expression of different CCNs and CDKs is regulated by CDCA2 depending on the cancer type." (PMID 35694386, 2022). "Then, the elevated expression and oncogenic functions of CDCA2 were demonstrated in several cancer types." (PMID 35694386, 2022). "CDCA2 promotes the tumorigenesis and development of prostate cancer, malignant melanoma, renal cancer, and other malignant tumors by promoting the proliferation of tumor cells." (PMID 35372372, 2021). "CDCA2 promotes the tumorigenesis and development of several types of cancers by promoting the proliferation of tumor cells." (PMID 35372372, 2021).
cancer (continued). "All data clearly indicated that CDCA2 was overexpressed in PCa and is a candidate oncogene for PCa and multiple other cancers." (PMID 32509575, 2020). "What is more, higher CDCA2 expression was correlated to patients' survival in some cancer types, such as in LAUD, KIRP, and LIHC." (PMID 32509575, 2020). "To our great interest, we found CDCA2 was not only overexpressed in PCa but also upregulated in at least 18 cancer types in the TCGA dataset." (PMID 32509575, 2020). "CDCA2’s significance in cancer development has recently received increasing attention." (PMID 37733705, 2023). "CDCA2 was extensively examined in our work to determine its role in a wide range of cancers." (PMID 37733705, 2023). "CDCA2 is shown to be differentially expressed in a wide variety of cancers." (PMID 37733705, 2023). "Studies have found that CDCA2 is related to the occurrence and development of various cancers." (PMID 37733705, 2023). "However, to the best of our knowledge, no systematic and comprehensive studies on the diagnosis, prognosis, and related biological functions of CDCA2 in pan-cancer, especially in LGG have been reported." (PMID 37733705, 2023). "Our study indicates that CDCA2 may not only serve as a promising biomarker for the diagnosis and prognosis of diverse cancers, but also as an appealing target for LGG therapy." (PMID 37733705, 2023). "An increased expression of the CDCA2 gene in humans has been found in malignant neoplasms." (PMID 35893074, 2022). "A growing body of evidence has revealed that CDCA2 is a crucial factor in cancer development." (PMID 36588796, 2022). "In all 33 TCGA cancer types, 18 of them exhibited significantly higher CDCA2 expression." (PMID 32509575, 2020). "Our result suggests that CDCA2 was overexpressed in PCa and many other cancer types." (PMID 32509575, 2020). "We further examined the expression of CDCA2 in other cancer types." (PMID 32509575, 2020). "Furthermore, CDCA2 expression were raised in all five cancer cell lines compared to NCM460 cells in both protein and mRNA levels." (PMID 31196027, 2019). "We continued investigating the expression of CDCA2 in cancer cell data using the CCLE database." (PMID 29467944, 2018). "Moreover, CDCA2-dependent DDR regulation is strengthened by CDCA2 over-expression during cancer progression, resulting in reduced DDR sensitivity." (PMID 24905922, 2014). "Furthermore, CDCA2-positive cases were correlated significantly (P<0.05) with high cancer progression." (PMID 23418564, 2013). "To investigate mRNA and protein expression of CDCA2 identified as a cancer-related gene in our previous microarray data, we performed qRT-PCR and Western blot analyses using six OSCC-derived cell lines (HSC-2, HSC-3, HSC-4, Ca9-22, Ho-1-u-1, and Sa3), the HeLa cell line, and the HNOKs." (PMID 23418564, 2013). "Specifically, CDCA2 and CDCA8 play significant roles in cell division and chromosome segregation, and mutations in these genes may lead to chromosomal instability, a characteristic feature of many cancers, including GBM." (PMID 40114265, 2025). "Subsequently, the expressions of CDCA2, CDCA3, CDCA4, CDCA5, CDCA7, and CDCA8 genes in COAD samples across various cancer stages were verified using the GEPIA2 database." (PMID 39924497, 2025). "Through CDCA2 knockdown, this study highlights the dual role of CDCA2 in regulating cellular behaviors in SW480 cells, with significant implications for cancer biology." (PMID 39924497, 2025). "Further exploration of CDCA2 and CDCA3 effects on the tumor microenvironment and metastasis is essential to develop balanced strategies for effective cancer treatment." (PMID 39924497, 2025). "The analyses of GTEx, TCGA, and ICGC data revealed that CDCA2 was overexpressed in HCC, compared with most healthy organs, with high sensitivity and specificity for the diagnosis of this carcinoma." (PMID 34660326, 2021). "It has been reported that ESCO2, CDCA2 and CENPA are cell cycle-related genes involved in cancer progression." (PMID 29642861, 2018).
cancer (continued). "The link between proliferation, CDCA2, and PI3K signaling has been reported in other cancer types." (PMID 40565058, 2025). "Among them, seven genes of CDCAs (CDCA1/NUF2: P = 2.73E-22, CDCA2: P = 1.52E-16, CDCA3: p = 1.50E-20, CDCA5: P = 1.77E-20, CDCA6/CBX2: P = 6.87E-19, CDCA7: P = 5.92E-16, and CDCA8: P = 1.67E-18) were all up-regulated in 19 cancer datasets." (PMID 33665158, 2020). "Additionally, the absence of significant differences in the mRNA expression levels of CDCA2, CDCA3, CDCA4, CDCA5, CDCA7, and CDCA8 across different cancer stages of COAD suggests that these genes may play a consistent role throughout the progression of COAD." (PMID 39924497, 2025).
tumor (27 papers, 2012 to 2025). "CDCA2 overexpression in hepatocellular carcinoma and colorectal cancer has also been associated with increased tumor cell proliferation, invasive behavior, and resistance to apoptosis, indicating a role in promoting treatment resistance." (PMID 40114265, 2025). "In DLBCL xenograft mice, loss of CDCA2 reduced the tumor growth rate, in agreement with the slower proliferation confirmed in cell culture studies." (PMID 40565058, 2025). "Another NUPR1-regulated gene, the cell cycle-associated 2 gene (CDCA2) is typically overexpressed in tumor cells and is positively correlated with tumor proliferation." (PMID 33801927, 2021). "CDCA2 belongs to the family of cell division cycle associated proteins (CDCAs), which are critical to tumor progression in a growing body of evidence." (PMID 34660326, 2021). "The correlations between CDCA2 protein expression and the clinicopathological characteristics of the patients were analyzed, and the results showed an association of high CDCA2 protein expression with high tumor grade (P = 0.0405) and Glypican-3 positivity (P = 0.049)." (PMID 35694386, 2022). "In addition, IHC staining for the proliferation marker Ki67 revealed that expression of Ki67 was negatively associated with CDCA2 in dissected tumor mass, indicating that CDCA2 repression led to inhibition of tumor cell proliferation." (PMID 32509575, 2020). "Our study revealed that CDCA2 expression was associated with tumor progression." (PMID 31196027, 2019). "The tumor growth was significantly reduced in CDCA2-KO xenograft tumors in comparison to SCR tumors, resulting in longer survival time." (PMID 40565058, 2025). "The results suggested correlations between high CDCA2 expression and lower age (P = 0.0213), advanced clinical stage (P = 0.0001), and higher tumor grade (P = 0.0011)." (PMID 35694386, 2022). "Although not statistically significant, there were higher percentages of high-CDCA2 samples in groups with advanced clinical stage and larger tumor size." (PMID 35694386, 2022). "Regarding PAAD, increased CDCA expression along with advanced PAAD tumor stage, NUF2, CDCA2, CDCA3, CDCA4 and CDCA5 expression are risk factors for poor prognosis, while CBX2 expression is a protective factor (P < 0.05)." (PMID 33437202, 2021). "The neoantigen load had significant differences in CDCA1, CDCA2, and CDCA8, which indicated that these genes with low-methylation had powerful associations with weakening tumor immunogenicity." (PMID 33665158, 2020). "All these results reveal that the methylation states of CDCA1, CDCA2, and CDCA8 have strong associations in the tumor immunogenicity." (PMID 33665158, 2020). "We found that knockdown of CDCA2 inhibited tumor growth, leading to significantly reduced tumor volumes and mass but not body weight." (PMID 32509575, 2020). "Our data indicated that CDCA2 was highly expressed in 58% (52/90) of PCa tumor samples but with only 24% (22/90) frequency in BPH (p = 0.0001)." (PMID 32509575, 2020). "Obviously, high CDCA2 expression was significantly related to larger tumor size (P = 0.002) and lymph node invasion (P = 0.011)." (PMID 31196027, 2019). "To assess the oncogenic role of CDCA2 in vivo, we established xenograft tumor models using A549 cells transfected with sh-NC or sh-CDCA2." (PMID 28423619, 2017). "The average tumor volume and weight in the sh-CDCA2 group were significantly lower than those in the sh-NC group." (PMID 28423619, 2017). "Consistent with findings in TCGA, chi-square test also revealed that CDCA2 expression positively correlated with differentiation (P = 0.020), primary tumor size (P = 0.0025) and TNM stage (P = 0.0171)." (PMID 28423619, 2017). "In conclusion, our study suggests that CDCA2 is widely upregulated in LAC, and high level of CDCA2 correlates with more advanced tumor stage and worse prognosis." (PMID 28423619, 2017).
tumor (continued). "By analyzing TCGA_LUAD_exp_HiSeqV2-2015-02-24 dataset, we found that mRNA expression of CDCA2 was upregulated in 54 (94.7%) LAC tissues out of the 57 paired tissues (the tumor and the paired normal lung tissue from a same patient)." (PMID 28423619, 2017). "Chi-square test revealed that CDCA2 mRNA expression was significantly correlated with sex (p < 0.0001), primary tumor size (p = 0.0003) and TNM stage (p = 0.0024)." (PMID 28423619, 2017). "Xenograft assay also showed that depletion of CDCA2 suppressed tumor growth in vivo with decreased expression of CCNE1." (PMID 28423619, 2017). "Our results identified CDCA2 expression in human OSCCs and therefore parallel findings that CDCA2 is overexpressed in malignant tumor cell lines." (PMID 23418564, 2013). "Thus, the expression of CDCA2 in paired normal and tumor tissues from the TCGA database was also analyzed." (PMID 37733705, 2023). "Also, the methylation analysis of CDCAs indicated an association with the tumor immunogenicity, i.e., low-methylation of CDCA1, CDCA2, and CDCA8 dramatically reduced the immune infiltrate levels of T cells and cytotoxic lymphocytes." (PMID 36159969, 2022). "Also, the methylation analysis of CDCAs depicts the strong association with the tumor immunogenicity, i.e., low-methylation of CDCA1, CDCA2, and CDCA8 dramatically reduced the immune infiltrate levels of T cells and cytotoxic lymphocytes." (PMID 33665158, 2020). "In addition, results also indicate medium expression of CDCA2 in normal tissues and high expression in tumor tissues." (PMID 32716971, 2020). "To further evaluate the function of CDCA2 in vivo, we determined whether knockdown of CDCA2 could inhibit tumor xenograft growth in nude mice." (PMID 32509575, 2020). "And CDCA2 promoted the proliferation of tumor cells via activating the AKT/CCND1 pathway." (PMID 33665158, 2020). "Conversely, upregulation of CDCA2 induced malignant tumor cell behaviors, as indicated by the higher cell proliferation rate in CCK-8 assay, higher clonogenic survival in colony formation assay, and higher proportion of cells in the DNA replication phase in the EdU assay." (PMID 31196027, 2019). "Thus, the alteration of oncogenic pathway and upregulated tumor suppressors might play a role in induction of apoptosis and inhibition of cellular proliferation when CDCA2 is repressed." (PMID 32509575, 2020). "Thus, our data demonstrated that knockdown of CDCA2 inhibited tumor growth in vivo." (PMID 32509575, 2020). "For example, CDCA2, CDCA3, and CDCA8 exhibited moderate positive correlations with the immune checkpoint CD276, suggesting that higher CDCA expression might be associated with increased levels of CD276, potentially aiding immune evasion in the tumor microenvironment." (PMID 40114265, 2025). "Across CDCA2, CDCA3, CDCA4, CDCA5, CDCA7, and CDCA8, we observed significantly lower promoter methylation levels in primary tumor samples compared to normal samples, suggesting hypomethylation of these genes in GBM tumors." (PMID 40114265, 2025). "An examination of tumor specimens revealed an escalation in the expression of KIF18A, in conjunction with heightened levels of CENPE, SNHG4, KIAA1841, CDCA2, and PRR11 mRNA." (PMID 38495502, 2024). "We found significantly upregulated CDCA2 expression in HCC, which was correlated with higher clinical stage, tumor grade and Glypican-3 (+)." (PMID 35694386, 2022). "For instance, the methylation levels of CDCA2 and CHAT were found to be approximately 20 times higher in the tumor group than that in the control group." (PMID 35126463, 2021). "After comparing the expression level of the tumor tissue and the paracancer tissue in each case, we found that the expression levels of CDCA2, CDCA3, CDCA5 and CDCA8 were overexpressed in tumor tissues in each patient." (PMID 32913466, 2020).
tumor (continued). "To further evaluate the clinical utility of CDCA2 in the prognosis of LAC patients, we applied our own LAC tissue microarray containing 92 pairs of LAC and matched non-tumor tissues with long time follow-up records." (PMID 28423619, 2017). "We confirmed that CDCA2 could promote the proliferation and colony formation of HCC cells, as in several other types of tumor cells, by facilitating G1/S transition while inhibiting cell apoptosis." (PMID 35694386, 2022). "CDCA2 can promote LAC cell proliferation in vitro and tumor growth in vivo." (PMID 28423619, 2017). "Nevertheless, for CDCA2, our results are in accordance with previous findings in pre-malignant (not cancerous) or tumor cells, in which the levels of CDCA2 determine the activation threshold of the DNA damage checkpoint." (PMID 24905922, 2014).
CDCA2 also shares sentences with these, for which no sentence is quoted: neuroblastoma (5 papers); adenocarcinoma (1); cervical squamous cell carcinoma (1); diffuse large B-cell lymphoma (1); head and neck squamous cell carcinoma (1); heart failure (1); Hyperinsulinemia (1); invasive breast carcinoma (1); invasive ductal breast carcinoma (1); invasive lobular breast carcinoma (1); lymph node metastasis (1); migraine (1); oligodendroglioma (1); ovarian tumor (1); Pan (1); pancreatic cancer (1); pancreatic ductal adenocarcinoma (1); preeclampsia (1); psoriasis (1); triple-negative breast carcinoma (1).